RNU7-133P (RNA, U7 small nuclear 133 pseudogene)
Gene: Small nuclear RNA gene on chromosome 6 (14,156,462 to 14,156,523, forward strand). Ensembl gene ENSG00000238987.
Homologues: Orthologues: chimpanzee U7 (100% identical), macaque U7 (95% identical). Paralogues in human: RNU7-57P (82% identical), RNU7-171P (81% identical), U7 (81% identical), RNU7-11P (79% identical), RNU7-22P (79% identical), RNU7-25P (79% identical), RNU7-29P (79% identical), U7 (79% identical), RNU7-124P (77% identical), RNU7-12P (77% identical), RNU7-13P (77% identical), RNU7-48P (77% identical), and 143 more.